MZF1 (myeloid zinc finger 1)
Diseases named in the same sentence as MZF1 in open-access papers (continued):
Sharing a sentence is not in itself a finding about the gene and the disease.
colorectal cancer (11 papers, 2013 to 2025). A primary or metastatic malignant neoplasm that affects the colon or rectum. "MZF1 activation has been implicated in the progression of cervical and colorectal cancer, where it increases invasion and metastasis, at least partially, via increased expression and activity of receptor tyrosine kinase AXL." (PMID 31963147, 2020). "In contrast, in colorectal cancer, the overexpression of MZF1 enhances the invasiveness and migratory potential of colon cancer cells." (PMID 40655141, 2025). "Depending on the cancer entity, Axl expression is further induced by the transcription factors Sp1 and 3 as well as myeloid zinc finger 1 (Mzf1) in colorectal cancer patients." (PMID 34771611, 2021). "MZF1 directly binds to the p55PIK promoter to activate its expression, and acts as a growth accelerator in colorectal cancer cells." (PMID 27259238, 2016). "Over-expression of MZF1 aggressively induces the transformation of NIH3T3 cells, and increases the migration and invasion of colorectal cancer cells, indicating the oncogenic functions of MZF1 in tumor progression." (PMID 27259238, 2016). "Taken together, we concluded that p55PIK is transcriptionally activated by MZF1, resulting in increased proliferation of colorectal cancer cells." (PMID 23509792, 2013). "However, depletion of AXL by RNA interference only partially inhibits MZF1-induced migration and invasion of colorectal cancer cells, suggesting that additional MZF1-regulated genes are involved in this process." (PMID 31963147, 2020). "The same investigators also reported on the importance of the Myeloid zinc finger 1 (MZF1) binding to the AXL promoter and regulating its expression in cervical (HeLa) and colorectal cancer (Rko) cells." (PMID 35572601, 2022). "Over-expression of MZF1 leads to transactivation of anexelekto (AXL) promoter and increase of migratory, invasive, and metastatic potential of colorectal cancer cells." (PMID 32042322, 2020). "Moreover, GSK3β reduces MZF1 expression, leading to c-MYC downregulation in colorectal carcinoma." (PMID 36499054, 2022).
lung adenocarcinoma (11 papers, 2015 to 2023). A carcinoma that arises from the lung and is characterized by the presence of malignant glandular epithelial cells. "Studies demonstrated that Myc transcription was upregulated by liver kinase B1 loss-mediated expression of MZF1, and the MZF1/Myc axis was responsible for migration and invasion in lung adenocarcinoma cells." (PMID 32929338, 2020). "In lung adenocarcinoma cells, liver kinase B1 loss-induced MZF1 expression promotes the transcription of c-Myc, and is responsible for the growth, migration and invasion of cancer cells." (PMID 27259238, 2016). "Furthermore, a recent study showed that the MZF1 (Myeloid Zinc Finger 1)/c-MYC axis is essential for progression of lung adenocarcinomas; it is mediated by the cellular loss of the wild-type liver kinase B1 gene, i.e. a tumor suppressor frequently repressed in the pathogenesis of epithelial cancers." (PMID 26427040, 2015). "High expression of SCAND2 and MZF1 was significantly correlated with enhanced prognosis of patients suffering from lung adenocarcinoma." (PMID 36982267, 2023). "Additionally, MZF1 could positively modulate the expression of c‐Myc, and MZF1‐regulated c‐Myc expression may enhance the progression of lung adenocarcinoma." (PMID 33533172, 2021). "In lung adenocarcinoma, LKB1-depleted cells promote cancer cell growth, spread, and invasion through the MZF1/MYC axis." (PMID 37654657, 2023). "MZF1 facilitates the transcription of c-MYC, and is responsible for growth, migration, and invasion of lung adenocarcinoma cells." (PMID 32042322, 2020). "MZF1 may be involved in an early stage of hematopoiesis and plays a role in terminal differentiation–especially of granulocyte lineage, it has also been shown to regulate c-MYC expression in lung adenocarcinoma." (PMID 27551915, 2016).
gastric cancer (9 papers, 2016 to 2025). A primary or metastatic malignant neoplasm involving the stomach. "Notably, the immunostaining of MZF1 was associated with MMP-14 immunoreactivity in gastric cancer cases (correlation coefficient R = 0.500, P < 0.001)." (PMID 27259238, 2016). "HIF-2α and SP1 promote MT1-MMP expression in Von Hippel–Lindau renal cell carcinoma (VHL RCC), while in gastric cancer, myeloid zinc finger 1 (MZF1) has been shown to upregulate MT1-MMP expression." (PMID 39937000, 2025). "A similar dual role of MZF1 has been observed in gastric cancer, where it functions both as an oncogene and a tumor suppressor." (PMID 40655141, 2025). "Previous studies have shown that metallothionein 2A (MT2A) is downregulated in gastric cancer cells and exerts its anti-gastric cancer effect by binding to MZF1 to target NFKBIA23." (PMID 38443583, 2024). "In gastric cancer, myeloid zinc finger 1 (MZF1) upregulates MMP14 expression, which can be competitively inhibited by miR-337-3p because this miRNA can bind to the same binding site of MZF1 on the promoter of MMP14." (PMID 34297054, 2021). "On the contrary, higher levels of MT2A are associated with favorable outcome in patients with gastric cancer, and MT2A exerts anti-gastric cancer effects by complexing with MZF1 to target NFKBIA." (PMID 34663301, 2021). "In the same study it was shown that in the clinical samples, MZF1 expression correlated positively with MMP14 expression in gastric cancer." (PMID 31963147, 2020). "On the contrary to this, another study where human gastric cancer samples were analyzed indicated that MZF1 expression was decreased during gastric cancer progression, which correlated with increased invasiveness of gastric cancer." (PMID 31963147, 2020). "In gastric cancer, miR-337-3p inhibit myeloid zinc finger 1 (MZF1) induced transcriptional activation of MMP-14 through recruiting Ago2 and inducing repressive chromatin remodeling." (PMID 29471827, 2018). "Gain- and loss-of-function studies demonstrated that miR-337-3p suppressed the growth, invasion, metastasis, and angiogenesis of gastric cancer cells in vitro and in vivo through repressing MZF1-facilitated MMP-14 expression." (PMID 27259238, 2016). "Dual-luciferase assay indicated that ectopic expression or knockdown of MZF1 enhanced and attenuated the promoter activity of MMP-14 in gastric cancer cells, respectively, and mutation of MZF1 binding site abolished these effects." (PMID 27259238, 2016). "Significant difference was noted among the survival curves of gastric cancer patients with low or high expression of miR-337-3p, MZF1, or MMP-14." (PMID 27259238, 2016). "Stable transfection of MZF1 into gastric cancer cells resulted in enrichment of MZF1 on the MMP-14 promoter." (PMID 27259238, 2016). "In clinical specimens and cell lines of gastric cancer, MZF1 was highly expressed and positively correlated with MMP-14 expression." (PMID 27259238, 2016). "The tube formation of endothelial cells was increased by treatment with the medium preconditioned by stable transfection of gastric cancer cells with MZF1." (PMID 27259238, 2016). "The MZF1 immunoreactivity was significantly higher in gastric cancer cases with deeper gastric wall invasion (P < 0.001), lymph node metastasis (P < 0.001), distant metastasis (P = 0.029), and advanced tumor-node-metastasis (TNM) stage (P < 0.001)." (PMID 27259238, 2016). "In matrigel invasion assay, gastric cancer cells stably transfected with MZF1 presented an increased invasion capacity than mock cells." (PMID 27259238, 2016). "Higher protein and transcript levels of MZF1 or MMP-14 were observed in gastric cancer tissues than those in normal gastric mucosa, which was in line with the results from public datasets." (PMID 27259238, 2016). "Nuclear run-on assay demonstrated that stable over-expression of MZF1 increased the nascent transcript levels of MMP-14 in gastric cancer cells, than those in mock cells." (PMID 27259238, 2016).
gastric cancer (continued). "In this study, we demonstrated that MZF1 is highly expressed in gastric cancer, and is an independent prognostic factor for unfavorable outcome of patients." (PMID 27259238, 2016). "We found that knockdown of MZF1 suppressed the growth, invasion, and angiogenesis of gastric cancer cells, suggesting the oncogenic functions of MZF1 during the progression of gastric cancer." (PMID 27259238, 2016). "miR-337-3p was an independent prognostic factor for favorable outcome of gastric cancer, and patients with high MZF1 or MMP-14 expression had lower survival probability." (PMID 27259238, 2016). "Our findings showed that miR-337-3p was an independent prognostic factor for favorable outcome of gastric cancer, and suppressed the expression of MMP-14 through repressing the enrichment of MZF1 on MMP-14 promoter in gastric cancer cells." (PMID 27259238, 2016). "Some studies have suggested that MZF1 expression correlates with poor prognosis in gastric cancer." (PMID 40655141, 2025). "Consequently, in the same study, miRNA-337-3p was shown to inhibit growth, invasion, metastasis, and angiogenesis of gastric cancer cells in vitro and in vivo via repression of MZF1 activity." (PMID 31963147, 2020). "In gastric cancer cells, MZF1 upregulates MMP14 expression by directly binding to its promoter." (PMID 31963147, 2020). "On the other hand, we examined the effects of MZF1 knockdown on gastric cancer cells." (PMID 27259238, 2016). "Meanwhile, miR-337-3p is under-expressed in human gastric cancer, and suppresses the transcription of MMP-14 via epigenetically suppressing the binding of MZF1 to its promoter, resulting in decreased growth, invasion, metastasis, and angiogenesis of gastric cancer cells in vitro and in vivo." (PMID 27259238, 2016). "This study extends our knowledge about the regulation of MMP-14 at transcriptional level, and suggests that MZF1 and miR-337-3p may be of potential values as novel therapeutic targets for human gastric cancer." (PMID 27259238, 2016). "In this study, we demonstrated that MMP-14 was a novel target gene of MZF1 in gastric cancer." (PMID 27259238, 2016). "To address the hypothesis that MZF1 may influence the MMP-14 expression in gastric cancer cell lines, we performed the MZF1 over-expression and knockdown experiments." (PMID 27259238, 2016). "Although MZF1 and miR-337-3p are found to be independent prognostic factors, a larger series of clinical specimens are needed to further explore the cooperative effects of high MZF1 expression and low miR-337-3p levels on the outcome of gastric cancer patients." (PMID 27259238, 2016). "Finally, endogenous MMP-14 expression, both transcript and protein, was increased or decreased by over-expression and knockdown of MZF1 in gastric cancer cells, suggesting that MZF1 may facilitate the MMP-14 expression by activating transcription." (PMID 27259238, 2016). "The fact that over-expression of miR-337-3p was sufficient to prevent the gastric cancer cells from MZF1-facilitated biological behaviors indicates that miR-337-3p exerts its tumor suppressive functions, at least in part, through repressing the MZF1 activity in gastric cancer." (PMID 27259238, 2016). "In gastric cancer, MZF1 interacts with HMGB3 to regulate the expression of target genes, thereby influencing the proliferation, metastasis, and invasion of gastric cancer cells." (PMID 40655141, 2025). "We analyzed the relationship between the expression of ISGF-3, MZF1, SRF, and TBP and the prognosis of stomach cancer patients by the Kaplan–Meier plotter database." (PMID 35712475, 2022). "However, the downstream genes of MZF-1 in gastric cancer still remain unknown." (PMID 27259238, 2016). "Taken together, these data indicate that miR-337-3p directly binds to the MMP-14 promoter to repress MZF1-facilitatd MMP-14 expression, thus suppressing the progression of gastric cancer." (PMID 27259238, 2016).
gastric cancer (continued). "In summary, we have shown that MZF1 is highly expressed and directly binds to the MMP-14 promoter to facilitate its transcription in gastric cancer." (PMID 27259238, 2016). "First, the expression of MZF1 and MMP-14 was positively correlated in gastric cancer tissues and cell lines." (PMID 27259238, 2016). "Higher MZF1 and MMP-14 levels were observed in gastric cancer cell lines than those in normal gastric epithelial cells." (PMID 27259238, 2016). "We demonstrate, for the first time, that MZF1 is highly expressed and facilitates the transcription of MMP-14 in gastric cancer." (PMID 27259238, 2016). "We demonstrated that MZF1 directly bound to the MMP-14 promoter to facilitate its nascent transcription and expression in gastric cancer cell lines." (PMID 27259238, 2016). "Further analysis of Gene Expression Omnibus (GEO) datasets indicated the positive correlation between MZF1 and MMP-14 levels in different gastric cancer cohorts." (PMID 27259238, 2016). "Western blot and real-time quantitative RT-PCR were applied to measure the expression levels of MZF1, MMP-14, and miR-337-3p in 90 gastric cancer specimens and normal gastric mucosa." (PMID 27259238, 2016). "Since above evidence indicated that miR-337-3p attenuated the binding of MZF1 to MMP-14 promoter, we further investigated the effects of miR-337-3p over-expression on MZF1-facilitated MMP-14 expression in gastric cancer cells." (PMID 27259238, 2016). "The results show that the expression of ISGF-3, TBP, MZF1, and SRF is significantly related to the survival of stomach cancer patients (ISGF-3: HR = 0.47, log-rank P = 1.1e-11; TBP: HR = 1.76, log-rank P = 5.5e-11; SRF: HR = 1.76, log-rank P = 5.5e-11; MZF1B: HR = 1.8, log-rank P = 1.7e-11)." (PMID 35712475, 2022). "MiRNA-337-3p inhibits gastric cancer progression by downregulating MZF1 activity via a specific mechanism, where miRNA-337-3p binds to the promoter region of MMP14 adjacent to its MZF1 binding site and represses the MZF1-induced expression of MMP14." (PMID 31963147, 2020). "Notably, there was a positive correlation between MZF1 and MMP-14 transcript levels in gastric cancer tissues (correlation coefficient R = 0.797, P < 0.001)." (PMID 27259238, 2016).
lung squamous cell carcinoma (8 papers, 2020 to 2025). "For example, FTO upregulation has been shown to drive tumor growth via MZF1 in squamous cell lung carcinoma." (PMID 40722726, 2025). "The overexpression of FTO decreased m6A levels in MZF1 mRNA transcripts, increased mRNA stability, and promoted MZF1 expression, leading to the proliferation and invasion of lung squamous cell carcinoma cells." (PMID 36139662, 2022). "FTO is considered as a prognostic factor of lung squamous cell carcinoma, promoting cell proliferation and invasion, but inhibiting cell apoptosis by regulating the expression of MZF1." (PMID 35064107, 2022). "For instance, FTO plays an oncogenic role in lung squamous cell carcinoma by decreasing m6A levels and mRNA stability of MZF1." (PMID 36105083, 2022). "FTO showed oncogenic functions in lung squamous cell carcinoma, enhancing MZF1 expression by decreasing the m6A levels and mRNA stability in MZF1 mRNA transcripts." (PMID 33879631, 2021). "FTO can enhance the stability of MZF1 mRNA by reversing m6A modification, inducing MZF1 expression and ultimately promoting the progression of lung squamous cell carcinoma." (PMID 33029866, 2020). "Lung squamous cell carcinoma (LUSC) demonstrates heightened expression of FTO, which drives the expression of the oncogene MZF1 by decreasing m6A levels and mRNA stability within the MZF1 mRNA transcript." (PMID 38706740, 2024).
hepatocellular carcinoma (6 papers, 2015 to 2025). A malignant tumor that arises from hepatocytes. "MZF1 has also been implicated in increased expression of PKCα in hepatocellular carcinoma with reported reduction in invasion, migration, and proliferation in these cells with MZF1 siRNA." (PMID 26697505, 2016). "Depletion of MZF1 with specific antisense oligonucleotides reduces proliferation, migration and invasion of hepatocellular carcinoma cells and suppresses the growth of the corresponding xenografts." (PMID 31963147, 2020). "In hepatocellular carcinoma, MZF1 enhances the transcription of protein kinase C alpha (PKCα), thus facilitating the migration and invasion of cancer cells." (PMID 32042322, 2020). "This study uses the human hepatocellular carcinoma (HCC) model to demonstrate that MZF-1 and Elk-1 directly bind to the PKCα promoter and modulate PKCα performance through the interactive cooperation between the two transcription factors." (PMID 26010542, 2015). "In this study, the molecular mechanism of protein kinase C alpha (PKCα) gene regulation in hepatocellular carcinoma (HCC) involving Ets-like protein-1 (Elk-1) and myeloid zinc finger-1 (MZF-1) was investigated." (PMID 26010542, 2015).
melanoma (6 papers, 2017 to 2025). A malignant, usually aggressive tumor composed of atypical, neoplastic melanocytes. "Hypomethylation and myeloid zinc finger 1 (MZF1) overexpression promote PRAME expression in A375P melanoma cells." (PMID 40961095, 2025). "For example, PRAME expression is promoted by MZF-1, which leads to the enhancement of colony-forming capability of melanoma cells, and is inhibited by miR-211 in malignant melanoma cells." (PMID 38132219, 2023). "In the GSE91061 melanoma cohort, found that MZF1 expression was negatively correlated with response to anti-PD-1 treatment, with patients exhibiting lower MZF1 expression showing significantly better survival outcomes than those with higher MZF1 expression." (PMID 40655141, 2025). "Similarly, hypomethylation, in cooperation with MZF1, enhances PRAME expression in melanoma." (PMID 40961095, 2025). "The effect of methylation on MZF1-targeted DNA binding motifs has previously been described for the reprogramming key gene OCT4 in induced pluripotent stem cells, the PAX2 gene in endometrial cancer, and the tumour antigen PRAME (preferentially expressed antigen in melanoma) in melanoma cells." (PMID 35409379, 2022).
colon cancer (5 papers, 2016 to 2025). "It was found that, in colon cancer cells, MZF1 promotes proliferation by binding to the promoter of the receptor tyrosine kinase (Axl) and activating the promoter, thereby increasing the expression level of Axl." (PMID 36358661, 2022). "In conclusion, MZF1 has both carcinogenic and tumor-suppressive effects on colon cancer." (PMID 36358661, 2022). "Additionally, several investigations have demonstrated that Myeloid zinc finger 1 (MZF1) has dual functions in colon cancer, which may both promote cancer proliferation and inhibit cancer progression through apoptosis." (PMID 36358661, 2022). "Moreover, in colon cancer, some ZFP functions seem to have a dual, opposing role to MZF1." (PMID 36358661, 2022).
gastric adenocarcinoma (5 papers, 2022 to 2025). "The expression of miR-328-3p is directly activated by MZF1 in stomach adenocarcinomas, leading to reduced tumor growth." (PMID 36499054, 2022). "MZF1 expression was significantly elevated in gastric adenocarcinoma compared to normal tissues." (PMID 40655141, 2025). "As a transcription factor of Smad4, MZF1 directly binds to the core region of the Smad4 promoter, stimulates transcriptional activity, upregulates the expression of Smad4, and then inhibits the migration ability of gastric adenocarcinoma cells." (PMID 37654657, 2023). "However, MZF1 has also been shown to play a tumor suppressor role in stomach adenocarcinoma." (PMID 36499054, 2022).